SOX2 (SRY-box transcription factor 2)
Diseases named in the same sentence as SOX2 in open-access papers (continued):
Sharing a sentence is not in itself a finding about the gene and the disease.
cancer (continued). "In our experiments, we observed reduced levels of stem cells markers, both Sox2 and Nanog in CTCL cells, upon silencing of MALAT1, which is a clear indication that MALAT1 promotes cancer stem cell phenotype as silencing of MALAT1 reduces stem cell markers." (PMID 36059695, 2022). "To further investigate the relationship between cancer stem cell-like properties and CMTM2, we detected the expression of stem cell markers SOX2, NANOG, and CD44 in SGC7901 cells using qRT-PCR and western blotting." (PMID 35873650, 2022). "The significance of IL20RA as a biomarker in cancer has been addressed, and overexpression of IL20RA alone promotes cancer stemness via the transcription factor SOX2 and induces an immunosuppressive TME by increasing PD-L1 expression." (PMID 36284349, 2022). "BCSCs play an important role in cancer metastasis due to the aberrant expression of some stemness-related factors, such as CD44, SOX2, OCT4, c-MYC, KLF4, Nanog, and SALL4." (PMID 35740529, 2022). "SOX2 and ALDH1 OE was found in cancer cells, particularly in HGSC, with higher tumorigenicity and invasion abilities." (PMID 35162954, 2022). "CD24 in combination with CD44 and/or CD133 (PROM1) has been highlighted as cancer stem cell markers (in combination with NANOG, OCT3/4, and SOX2), and a cell‐type‐dependent correlation of CD24 to the chemokine receptor CD184 (CXCR4) has been shown." (PMID 34293822, 2022). "Cancer stemness markers, OCT4, SOX2, and NANOG, were found to be significantly decreased upon miR‐181a inhibition." (PMID 35029026, 2022). "For example de novo motif analysis revealed enrichment of potential cooperative factors that exert known roles in cancer progression (e.g., HIC2, KLF3, SOX2); the relative impact of these likely contributing factors should be assessed." (PMID 34773073, 2022). "Conversely, the mesenchymal markers fibronectin, N‐cadherin and vimentin, the EMT‐TFs Snail, Slug, Zeb1 and Zeb2, and the cancer stem cell markers CD44, Sox2 and Id1 were strongly induced by TGFβ and repressed by BMP in 3D cultures." (PMID 35348275, 2022). "Silencing of HIF-1α can suppress the expression of stem cell genes, in particular OCT4, SOX2, NANOG, and KLF4, thus preventing the progression of cancer." (PMID 36429127, 2022). "The regulating factors of cancer stemness were further measured, which indicated that TSAIII significantly downregulated the protein and mRNA expressions of SOX2, OCT4, Nanog and CD49f in a dose-dependent manner." (PMID 36612038, 2022). "Intriguingly, NEAT1 concomitantly increased the cancer stemness of TNBC cells and upregulated the expression of BMI1, OCT4, and SOX2." (PMID 35054896, 2022). "Consistently, the protein levels of pSTAT3, SOX2, CDA, and ABCC2 in cancer cells were decreased after silencing CAV1 in CAFs." (PMID 35045883, 2022). "Cancer cell stemness is regulated by a strong transcriptional circuit constituted by OCT4, SOX2, and NANOG." (PMID 36568166, 2022). "In fact, many germ cell markers were used to identify cancer stem cells, such as SSEA1, CD117, Sox2, PRDM14." (PMID 36435765, 2022). "We used Real-time PCR to detect the expression of cancer stem cell-related genes ALDH1, SOX-2, OCT-4, and Nanog." (PMID 35242031, 2022). "Nuclear NFAT transcriptionally activates the expression of several genes including NANOG, OCT4, SOX2, and FGF19 which are involved in cancer cell stemness." (PMID 35711942, 2022). "Our data suggest that the rapid and sustained upregulation of KDM6B following matrix detachment is necessary for SOX2 and CD44-mediated stemness to enhance anchorage-independent survival of various cancer patients’ cells." (PMID 35186918, 2022). "A plethora of cancer-associated markers such as CD133, CD44, ABCG2, aldehyde dehydrogenase, octamer binding transcriptional factor 4, SOX2, and NANOG have been reported in cancer stem cells." (PMID 35992863, 2022).
cancer (continued). "In this study, we present for the first time positive correlations of SHMT2 expression with the expression of cancer stem cell markers, such as OCT4, SOX2, and NANOG, and the aggressiveness of HNC." (PMID 36077112, 2022). "We also noticed the cancer stem cell gene signature SOX2 and EPCAM was clustered in the brown module, moreover, cancer stem cell has been reported exhibiting resistance to immunotherapy." (PMID 35768785, 2022). "Consistently, the protein levels of pSTAT3, SOX2, CDA, and ABCC2 in cancer cells were increased after incubation with miR-660-3p-silenced CAFs, while miR-660-3p overexpression in CAFs reversed this effect." (PMID 35045883, 2022). "SOX2 expression is fundamental to control self-renewal and malignant phenotypes in GBM cancer cells as well as in many stem cells, including pluripotent and neural types." (PMID 35921410, 2022). "Another in vitro study showed that the exomes secreted by preadipocytes (3T3L1 cells) influenced the differentiation, stemness, and migration of the cancer cells through miR-140/SOX2/SOX9 axis, which promote the progression of cancer." (PMID 35534879, 2022). "Expressions of cancer stem cell-related genes ABCG2, NANOG, ALDH1, OCT4, and SOX2 were significantly down-regulated in si-RSU1P2-1 and si-RSU1P2-2 groups compared to si-NC group (p < 0.05)." (PMID 35156514, 2022). "Up to now, Wnt/β-catenin signaling has been considered as the key factor in regulating cancer stem cells, and masses of cancer stemness-related genes (OCT4, ALDH1A1, LGR5, CD44, c-Myc, SOX2, and so on) are regulated by Wnt/β-catenin signaling." (PMID 36319622, 2022). "SOX2 and SOX9 are shown to interact during increased cancer stem cell content and the development of drug resistance." (PMID 35906698, 2022). "Recent studies have also revealed that SOX2 makes a contribution to chemoresistance and promotes EMT in different types of human cancers." (PMID 35309116, 2022). "The drug-resistance ability of cancer cells with significantly increased expression of stemness proteins, such as CD133, SOX2, and OCT4, is much stronger than those cells with either low or no stemness markers." (PMID 35184640, 2022). "SRY related HMG box gene 2 (SOX2) is a transcription factor that plays important roles in development, stem cell renewal, and cancer formation." (PMID 35055392, 2022). "Patient-derived primary culture cells, consisting of abundant cancer stem cells expressing CD133 and SOX2, were acquired and analyzed, and the effects of treatment with carmustine (BCNU) or (Z)-BP, in the presence/absence of TMZ, were evaluated." (PMID 35646111, 2022). "Of note, OCT4 together with SOX2 and NANOG were reported to reprogram the cancer cells to cancer stem cells (CSCs) and serve as major transcription factors maintaining the stemness of CSCs, and calcification or/and osteogenesis were noted in various cancers." (PMID 36581839, 2022). "For example, SOX2/SOX9-expressing CSCs produce Wnt inhibitor DKK1 and raise dormant CSCs (or LCC, latency competent cancer cells) with autonomous downregulation of NKG2DL that protect them from NK cell-mediated clearance." (PMID 35395787, 2022). "HIF-1 regulates expression of cancer stem cell markers like KLF4, MYC, OCT4, SOX2, and NANOG, and thus help cancer cells to survive through hypoxic crisis." (PMID 36253762, 2022). "Several studies have demonstrated that acute hypoxia selects for cancer cells with stem cell characteristics, enhancing stem-like cell marker expression, such as OCT4, SOX2, NANOG and MYC, through upregulation of the HIF-1α pathway." (PMID 36224457, 2022). "Of note, KIT+, ALDH1+ and SOX2+ cancer stem cell populations harbor proliferative and epithelial-like characteristics, while CD44+ and SOX9+ cancer stem cell populations demonstrate invasive and mesenchymal-like properties." (PMID 36171192, 2022). "We first measured the gene expression of cancer stemness-related factors, including CD44, CD133 and SOX2, which are major stemness markers of PCA." (PMID 35365766, 2022).
cancer (continued). "Accordingly, IFN-I exposure induced significant upregulation of Klf4, Oct3/4, Sox2, Nanog, hes family bHLH transcription factor 1 (Hes1) and Nes, and endowed MCA205 and AT3 cancer cells with increased sphere-forming ability." (PMID 36002648, 2022). "First, we used QPCR to detect several commonly used biomarkers of cancer stem cells, which are CD44, EpCAM, SOX2, C-MYC." (PMID 35816352, 2022). "Real-time PCR of MDA-MB-231 with increasing concentrations of a small molecular cancer stemness inhibitor, BBI-608, demonstrated stepwise decreases in expressions of Nanog, Sox2, and Oct4 stemness markers." (PMID 36284815, 2022). "miR-31 is clearly an oncogenic miRNA, upregulated in different cancer types, which was shown to regulate the stemness transcription factors Nanog/OCT4/Sox2 in cancerous tissue." (PMID 35215172, 2022). "Activation of the STAT3‐dependent pathways including the STAT3/FAK/ERK pathway, STAT3/Oct‐4 pathway in various cancer cells, and the IL‐8/STAT3 pathway and EGFR/STAT3/Sox‐2 pathways in TAMs are shown to contribute to the cancer stemness." (PMID 35356799, 2022). "We observed remarkably decreased Sox2 with either treatment, indicating that STAT3 maintains this marker of cancer stem cells." (PMID 34482626, 2022). "Like the master regulators OCT4, SOX2, and NANOG, multiple molecular signaling pathways that regulate cellular pluripotency are also dysregulated in cancer." (PMID 36118530, 2022). "Our data showed that GSK J4 treatment significantly reduces the transcript levels of SOX2, SOX9, and CD44 genes in detached cancer cells compared to the untreated control." (PMID 35186918, 2022). "We compared the expression levels (mRNA) of SOX B1 family members (SOX1, SOX2 and SOX3) in various cancers and normal tissue using the ONCOMINE database." (PMID 34953010, 2022). "The varied enrichment of OCT4 (POU5F1), SOX2, and NANOG in different types of cancer cells demonstrated the diversity of CSCs localization." (PMID 36451812, 2022). "Overall, we found that matrix detachment modulates the epigenome during anoikis, inducing KDM6A/B that positively regulates the expression of SOX2, CD44, and HIF1α to regulate survival and stemness of cancer cells." (PMID 35186918, 2022). "SOX2 and ALDH1 expression have been used as stemness markers for detecting cancer cell proliferation, migration, invasion and metastasis." (PMID 35162954, 2022). "It was demonstrated that cancer cells involved in VM show expression of CD133, CD44, ALDH, and Sox2, but also VE-cadherin and CD31." (PMID 36429127, 2022). "The knockdown of FOXM1 downregulated the CD44 and SOX2 CSC markers, which are involved in the emergence of CSCs in various types of cancers." (PMID 35887129, 2022). "By comparing the transcription levels of SOX B1 in pan‐cancer through ONCOMINE and GEPIA data sets, SOX2 was overexpressed in GBM and LGG and SOX3 had elevated expression in LGG." (PMID 34953010, 2022). "Following those phenotypes, it has been described that the expression of stem cell transcription factors, such as CD44, SOX2, CD133 ABCG2, and Nanog, play a pivotal role in determining the aggressiveness of cancer." (PMID 35884836, 2022). "It has been demonstrated that LINC-ROR regulates the pluripotency levels of TFs, including SALL4, LIN28, OCT4, SOX2, and NANOG via acting as a miRNA-145 sponge, leading to the preservation of hESCs and cancer stem cells undifferentiated status." (PMID 33745265, 2021). "It is well known that CSC stemness has been related to poor patient prognosis in several types of cancers whose properties are driven by transcription factors, the most important being OCT4, Sox2, and Nanog." (PMID 34830485, 2021). "We interrogated the CCLE data to determine the mRNA expression levels of SOX2 and EMT-inducing transcription factors in various cancer cell lines (n = 1156)." (PMID 34809669, 2021). "In the meantime, SPP1 overexpression promotes the expression of KLF4, NANOG, SOX2, and BMI1, which were cancer stem cell markers." (PMID 33996808, 2021).
cancer (continued). "Similar to cancer stem cells, we found that CD44hi IPF MPCs also express high levels of CXCR1 and show that IL-8 increases the expression of stemness markers Sox2 and Oct3/4 and promotes their self-renewal." (PMID 33822772, 2021). "The potential regulatory effects of DUXAP8 on the expression of the cancer stem cell marker, CD133, and stem cell-related genes, including OCT4, NANOG, and Sox2 were then investigated." (PMID 34957112, 2021). "CSC markers ALDH1A1, CD44, BMI1, OCT4, SOX2, and CD133 and their effects on cancer stemness, metastasis, prognosis, chemo/radiotherapy resistance and recurrence have been studied in HNSCC by our group and other researchers." (PMID 34359786, 2021). "The expression levels of cancer stem cell marker proteins ALDH1A1, C‐Myc, OCT4, NANOG, KLF 4 and SOX2 were found to be significantly higher in MCF‐7‐CSC than those in MCF‐7." (PMID 33305893, 2021). "Our data confirm that the SRR2 enhancer regulates SOX2 expression in cancer and reveal that SRR2 deletion halts malignant activity of SOX2." (PMID 33805518, 2021). "IGF/IGF-1R signaling has been reported to induce the expression of cancer stemness-related transcription factors, including IGF-1R, NANOG, OCT4, NFκB, STATs, SOX2, and YAP." (PMID 33669204, 2021). "Since SOX2, KLF4, and BMI1 are transcription factors which are mainly located in the nucleus of cancer cells, it was unlikely that circFAT1 regulated their expression directly." (PMID 34258151, 2021). "In other reports, c-MYC, SOX2, and NF-κB have been shown to regulate LIN28 expression in different model systems, including cancer." (PMID 34572725, 2021). "Cancer stemness was analyzed by detecting the ability of migration and invasion, NANOG, OCT4, and SOX2 expression, ALDH activity and sphere formation." (PMID 34656128, 2021). "With 10 identifiers, we observed that these genes interacted with stemness genes such as SOX-2 and NANOG, genes important in cancer pathways such as STAT3, CTNNB1, EGFR, TNF, and CASP3, and immune genes such as IL2 and CD4." (PMID 34685742, 2021). "As this phenotype is one of a characteristic of cancer stem cells (CSCs), stemness-related markers were tested: OCT-3/4, NANOG, SOX2, and ALDH1." (PMID 35127467, 2021). "Cancer-related genes commonly amplified from 3q26 include PIK3CA, TBL1XR1, DCUN1D1, SOX2, MECOM, PRKCI, and TERC." (PMID 34436017, 2021). "Consistently, FBP1 overexpression obviously inhibited the expression of SOX2, OCT4, and NANOG, which regulated CSC-like property in various cancers." (PMID 34363022, 2021). "Altogether, these reports and the present study highlight the importance and the biological relevance of the mutual regulation between SOX2 and GLI transcription factors in cancer." (PMID 33958721, 2021). "Increased expression levels of LGR5, PROM1, KLF4, SOX2, and MYC in HGD and cancerous tissues support the malignant phenotype and the existence of cancer stem cells and demonstrate that they can be used to assess diagnosis and prognosis." (PMID 34452555, 2021). "We also found that pluripotent transcription factors Sox2 and Oct4 were markedly up-regulated in IR-treated MCF7 cells as the ability of the cancer cells to grow and survive in anchorage-independent conditions has been widely accepted as a hallmark of CSCs." (PMID 34217266, 2021). "To verify that the spheres in our setup were enriched in cancer stem cells, we tested the expression of the stemness-related transcription factors POU5F1 (Oct4), SOX2, CD44, PROM1 (CD133), and NANOG in spheres and adherent cells 72 h after seeding." (PMID 34832951, 2021). "The expression of the stemness-associated markers OCT4, SOX2, NANOG, KFL4 and c-MYC by LA at the mRNA and protein level, and the unique expression patterns suggest a putative presence of CSC subpopulations within LA, which may be a novel therapeutic target for this cancer." (PMID 34685477, 2021).
cancer (continued). "This iron chelator inhibited the expression of Nanog, c-Myc, SOX2, OCT3/4, and KLF-4 in four cancer cell lines (HSC-2: Oral squamous cancer, TE-4, and OE33: Esophageal cancer, and NT-2: Embryonal cell carcinoma)." (PMID 35008527, 2021). "The mRNA expression of several cancer stemness genes including BMI1, Sox2, Oct4, and c-Myc, was upregulated in A400 cells." (PMID 34681614, 2021). "Stemness-related factors OCT4, SOX2, NANOG, and KLF4 are common transcriptional regulators in cancer stem cells." (PMID 33436575, 2021). "POLβ knockdown cells had a significant increase in NANOG, SOX2, C-MYC and OCT4 which are well-known markers of cancer stem cells." (PMID 34406589, 2021). "In cancer stem cells, Hedgehog signaling is known to drive the CSC phenotype through the regulation of stemness-determining genes such as Nanog, Oct4, and Sox2 and regulate self-renewal and differentiation of CSCs." (PMID 34445421, 2021). "In the Genomics of Drug Sensitivity in Cancer (GDSC) database, part of the 3q26 locus, including SOX2 and DCUN1D1 genes, is identified as a recurrent copy-number alteration in the pan-cancer analysis (feature cnaPANCAN246 in the database)." (PMID 34436017, 2021). "Several potential stem cell markers, including MSI1, ALDH1, SOX2, and OCT4, have been used to identify putative cancer stem cells of CC." (PMID 34858863, 2021). "Our results show that CEBPD can directly bind to the SOX2, OCT4, NANOG, and ABCA1 promoter regions to promote the properties of cancer stemness and drug resistance." (PMID 33436575, 2021). "Nonetheless, studies on the regulation of SOX-2 expression revealed that a neddylation inhibitor, MLN4924, can be used to target SOX-2 for anti-cancer therapy, which represses transcription of SOX-2." (PMID 34163000, 2021). "Results demonstrate that the extract, at IC50 doses, was able to significantly decrease the expression of CD44, CD24, NANOG, SOX-2, and OCT-4, indicating a reduction in the amount of cancer stem cells (CSCs) in the culture." (PMID 33572111, 2021). "In other cancers, deletion of LATS and the resultant up-regulation in YAP/TAZ activity resulted in uncontrolled expansion of Sox2-positive cells, whilst LATS1/2 activity can trigger self-renewal of cancer stem cells in aggressive oral cancer." (PMID 33557087, 2021). "In agreement, some intratumoral signaling crosstalk, e.g., glucose restriction, up-regulate the expression of pluripotency related genes SOX2, OCT4, and NANOG, increasing cancer stem cells." (PMID 33805347, 2021). "SOX2 maintains the stemness of CSC, ultimately resulting in cancer relapse and resistance to treatment." (PMID 33420101, 2021). "The role of transcriptional regulation has been widely studied in cancer, including discovery of MYC, Sox2, and the FOXO family as important players in cancer initiation and progression." (PMID 34408770, 2021). "They express cancer stem cell markers, such as CD34, MMP2, nestin, and SOX2, as well as the astro-neuronal lineage markers GALC, TUBB3 (CD56), and OLIG2." (PMID 34638987, 2021). "Consistent with the role of TGFβ in controlling cancer stemness, NS1643 also produced a strong inhibition of NANOG, SOX2, and OCT4 while arresting the cell cycle in G0/G1." (PMID 34885136, 2021). "SOX2 and OCT4 are highly expressed in cancer cells obtained from post-chemotherapy cancer patients compared to their pre-chemotherapy counterparts." (PMID 34200614, 2021). "In parallel, there was an increased expression of the pluripotency marker SOX2 as well as several EMT-markers, suggesting an enrichment of cells with cancer stem cell characteristics after treatment." (PMID 34172801, 2021). "Meanwhile, PC-9/GR/sh-BTK cells exhibited significantly lower levels of cancer stemness markers such as KLF4, SOX2, NANOG, and CD133, than its counterparts, whereas the pBTK-N1 cells expressed the highest levels of these markers." (PMID 34315851, 2021).